IL6 (interleukin 6)
Diseases named in the same sentence as IL6 in open-access papers (continued):
Sharing a sentence is not in itself a finding about the gene and the disease.
cholangiocarcinoma (85 papers, 2003 to 2026). A carcinoma that arises from the intrahepatic biliary tree (intrahepatic cholangiocarcinoma) or from the junction, or adjacent to the junction, of the right and left hepatic ducts (hilar cholangiocarcinoma). "Elevated IL-6 levels have been consistently reported in the serum and tumor microenvironment of patients with cholangiocarcinoma, particularly in inflammation-associated disease settings." (PMID 41557653, 2026). "In this study, we revealed the potential pathway of H19 that is targeted by let-7a/let-7b, causing the partial inactivation of IL-6 in its mediated inflammatory responses triggered by oxidative stress in cholangiocarcinoma." (PMID 27809873, 2016). "In the current study, we also show that levels of IL-6 in plasma are associated in a dose-dependent fashion with Opisthorchis-induced bile duct fibrosis (periductal fibrosis) and cholangiocarcinoma." (PMID 22629477, 2012). "To identify new targets for therapeutic intervention in cholangiocarcinoma, we postulated that a systematic approach based on ameliorating the phenotypic changes associated with IL-6 expression would be useful for identifying potential therapeutic agents." (PMID 21179572, 2010). "The inflammation-associated cytokine Interleukin-6 (IL-6) is increased in the biliary tract and in the systemic circulation in patients with cholangiocarcinoma." (PMID 21179572, 2010). "While the conditioned medium from cancer-associated fibroblasts dramatically increased IL-6-mediated cholangiocarcinoma cell motility, the conditioned medium from cancer associated fibroblasts pretreated with resveratrol entirely prevented cancer cell movement." (PMID 35566016, 2022). "Similarly, BEC autoreactive antibodies in patients with primary sclerosing cholangitis, a chronic liver disease that predisposes to cholangiocarcinoma formation, bind to and induce secretion of IL-6 from BECs." (PMID 34047814, 2021). "Similarly, the levels of AKT and IL6 can be decreased by genistein, which is associated with inhibitory effects on growth of cholangiocarcinoma cells." (PMID 33478536, 2021). "In cholangiocarcinoma, a significant reduction in IL-6 secretion was observed in the supernatant after 48 h of incubation (log concentration 3.37 vs. 2.32, p = 0.038)." (PMID 40426911, 2025). "For instance, in cholangiocarcinoma, IL‐6 inhibition has been shown to counteract gemcitabine resistance by suppressing STAT3 activation driven by IL‐6–producing cancer‐associated fibroblasts." (PMID 41189442, 2025). "Cholangiocarcinoma (CCA) is a typical inflammation-induced malignancy, and elevated serum interleukin-6 (IL-6) levels have been reported to be linked to the onset and progression of CCA." (PMID 38881895, 2024). "In conclusion, rLEL-Ov-TSP-3 stimulates cell proliferation and increases the production of pro-inflammatory cytokines, IL-6 and IL-8, leading to increased migration of both normal cholangiocyte and cholangiocarcinoma cell lines." (PMID 37752807, 2023). "Although IL-6 was shown to increase cell migration in cholangiocarcinoma cells, resveratrol was found to effectively counteract this effect." (PMID 35566016, 2022). "Cholangiocarcinoma cells secrete IL-6 and a little quantity of IL-8 in response to fibroblast-stimulated secretion in the conditioned media of cholangiocarcinoma-derived malignancy." (PMID 35566016, 2022). "In cholangiocarcinoma, both in vitro and in vivo experiments show that CAF-derived IL-6 impairs the autophagy-associated apoptotic response to 5-FU in cancer cells." (PMID 35488263, 2022). "Cholangiocarcinoma patients with low stromal IL-6 levels and active autophagy flux in the cancer cells have a better prognosis and more effective response to postoperative chemotherapy." (PMID 35488263, 2022). "The elevated plasma IL-6 increases risks of developing periductal fibrosis (a precancerous lesion) and cholangiocarcinoma to 19 and 150 times greater than a normal individual." (PMID 34948304, 2021).
cholangiocarcinoma (continued). "Overall, these complex observations of the role of IL-6 in human cholangiocarcinoma, showing both pro-tumorigenic and anti-tumorigenic properties, are “reproduced” in other types of cancers as well." (PMID 34047814, 2021). "H19 sponges let7a/let7b then mediate oxidative stress-induced IL-6 expression in cholangiocarcinoma." (PMID 33193379, 2020). "In cholangiocarcinoma cells, IL-6-dependent activation of PGRN increased cell proliferation by a mechanism involving protein kinase B (Akt) phosphorylation followed by nuclear exclusion of FOXO154." (PMID 32994489, 2020). "For example, H19 sponges let7a/let7b then mediate oxidative stress-induced IL-6 expression in cholangiocarcinoma." (PMID 33193379, 2020). "IL-6 has a direct effect on the expression of some miRNAs, and as chronic inflammation likely precedes cholangiocarcinoma, these miRNAs are more likely to be drivers of carcinogenesis." (PMID 30819129, 2019). "The inflammatory cytokine Interleukin-6 (IL-6) affects multiple intracellular pathways that contribute to cholangiocarcinogenesis and can be highly overexpressed in both cultured cholangiocarcinoma cell lines and surgically resected specimens." (PMID 30819129, 2019). "Several in vitro cell studies have been performed regarding cholangiocarcinoma, and all indicate that IL-6 has a pivotal effect on the growth and chemo-resistance of cholangiocarcinoma cells." (PMID 30038723, 2018). "Previous studies have shown that IL-6-induced Stat3 signaling upregulates Mcl-1 transcription in cholangiocarcinoma cells." (PMID 29899555, 2018). "In cholangiocarcinoma, the cytokine interleukin-6 (IL-6) is known to play a major role in tumor growth." (PMID 27911876, 2017). "Inhibition of interleukin-6 has been reported to specifically pose a growth-inhibition effect on cholangiocarcinoma cell line, and interleukin-6 overexpression will lead to activation of AKT and anti-apoptotic protein myeloid cell leukemia-1." (PMID 28415734, 2017). "For example, IL-6, one of the main inducers of CRP production, has been shown to be associated with development and progression of cholangiocarcinoma and other cancers." (PMID 27733196, 2016). "A recent study has also revealed that chronic inflammation and pro-inflammatory cytokines, like interleukin 6 (IL-6), play an important role in the development and progression of cholangiocarcinoma." (PMID 27733196, 2016). "In gastric and cholangiocarcinoma cell lines, proinflammatory cytokines including IL-1β, IL-6, and TNF-α have all been reported to induce Cdx2 gene expression." (PMID 26460825, 2015). "In a clinical setting, high levels of IL-6 following PDT of cholangiocarcinomas correlated positively with increased tumor mass, indicating that elevated IL-6 levels enhance tumor growth and/or recurrence following PDT." (PMID 26516076, 2015). "In cholangiocarcinoma, a high expression of the tumor suppressor gene regulator, gankyrin, favors tumor proliferation, invasion, and metastasis through activation of IL-6/STAT3 signaling pathway." (PMID 24901008, 2014). "Similar epigenetic silencing of SOCS3 has been seen in cholangiocarcinoma and colonic cancer, resulting in enhanced IL-6/STAT3 signalling and reduced apoptosis." (PMID 24757565, 2014). "IL-6, which has been shown to activate Mcl-1 transcription in PCa and cholangiocarcinoma cells through a signal transducer and activator of transcription 3 (Stat3)-dependent mechanism, was included as the positive control." (PMID 22276222, 2012). "It is only in the presence of these advanced pathologies (advanced fibrosis or cholangiocarcinoma) from chronic O. viverrini infection that significantly elevates plasma levels of IL-6 are observed." (PMID 22629477, 2012). "The role of IL-6 as a biological determinant of cholangiocarcinoma growth has been demonstrated in both cell culture and tumor cell xenograft models." (PMID 21179572, 2010).
cholangiocarcinoma (continued). "Increased production of Interleukin-6 promotes cholangiocarcinoma growth and contributes to chemoresistance by activating cell survival mechanisms." (PMID 21179572, 2010). "Autocrine expression of IL-6 has been described in cholangiocarcinoma cells, and IL-6 can promote the growth of malignant cholangiocytes in vitro." (PMID 21179572, 2010). "To evaluate the potential of this group of drug candidates as therapeutic agents for cholangiocarcinoma, we began by evaluating their cytotoxic potential in IL-6 producing cholangiocarcinoma cell lines." (PMID 21179572, 2010). "We sought to identify biologically active compounds capable of ameliorating the phenotypic effects of IL-6 expression and to explore their potential therapeutic use for cholangiocarcinoma." (PMID 21179572, 2010). "In recent studies, we have evaluated the role of IL-6 in growth regulation and chemotherapeutic responses in cholangiocarcinoma." (PMID 21179572, 2010). "In human cholangiocarcinoma, sustained IL-6/Stat3 signalling, enhanced Mcl-1 expression and resistance to apoptosis, is attributed to epigenetic silencing of SOCS3 by promoter hypermethylation." (PMID 19698101, 2009). "Serum IL-6 concentration is proposed as novel biomarker for diagnosis of cholangiocarcinoma but also for monitoring the response to different therapies." (PMID 27933122, 2009). "CpG island methylation is an attractive mechanism explaining sustained IL-6 signalling in human cholangiocarcinoma." (PMID 27933122, 2009). "SOCS-3 epigenetic silencing is responsible for sustained IL-6/STAT-3 signalling in cholangiocarcinoma." (PMID 27933122, 2009). "Interleukin-6 (IL-6)-mediated signal transducers activation is aberrantly sustained in cholangiocarcinoma cells, resulting in resistance to apoptosis." (PMID 27933122, 2009). "For example, interleukin-6, an inflammatory cytokine, promotes human cholangiocarcinoma cells grown in vivo by inhibiting apoptosis through the activation of miRNAs including miR let-7a and miR370, thereby modulating the activation of STAT-3 pathways." (PMID 19436294, 2009). "Evodiamine inhibits the proliferation and induces apoptosis of cholangiocarcinoma cells, inhibits the migration and invasion of cholangiocarcinoma cells, suppresses IL-6/STAT3 signal transduction by upregulating the expression of SHP-2, and treats cholangiocarcinoma." (PMID 39944619, 2025). "However, in chronic senescent conditions, IL-6 is produced by senescent cells to promote the over-proliferation of hepatic progenitor cells and contribute to hepatocellular-cholangiocarcinoma carcinogenesis." (PMID 38890694, 2024). "Blocking IL-6 trans-signaling using soluble gp130 or clearing senescent cells using a senolytic agent, as well as the depletion of hepatic progenitor cells, result in a significant reduction of hepatocellular-cholangiocarcinoma tumors." (PMID 38890694, 2024). "Taken together, these data suggest a crucial role of IL-6 in cholangiocarcinoma development, although it must be clarified whether it mainly exerts pro-tumorigenic or anti-tumorigenic functions." (PMID 38275386, 2023). "FXR expression was negatively correlated with IL-6 in intrahepatic cholangiocarcinoma tissues." (PMID 34047814, 2021). "However, it was shown that inhibition of IL-6 trans-signalling by the administration of recombinant sgp130Fc reduced cholangiocarcinoma cell line viability and induced apoptosis, whereas both migration and proliferation increased." (PMID 34047814, 2021). "During the tumorigenesis of cholangiocarcinoma, cholestasis and chronic inflammation may induce bile duct epithelial cells to produce variable cytokines including IL-6, IL-8, TGF-β1, TNF-α, platelet-derived growth factor, and epidermal growth factor." (PMID 30469416, 2018). "A recent study showed miR-17–92 was regulated by IL-6/STAT3 in cholangiocarcinoma cells." (PMID 29254202, 2017).
cholangiocarcinoma (continued). "Our aims for this study are to determine whether guava pulp (GP) has protective effects on cholestatic liver injury-induced mouse model and on interleukin-6 (IL-6) mediated proliferation of QBC939 cholangiocarcinoma cell line." (PMID 27335829, 2013). "Interleukin 6 (IL-6) is a potent mitogen for cholangiocytes and cholangiocarcinoma cells." (PMID 21388551, 2011). "Several reports show that cholangiocarcinoma cells constitutively secrete IL-6 which may activate ERK1/2 and AKT." (PMID 19445727, 2009). "The pretreatment of cholangiocarcinoma (CCA) cells with quercetin and EGCG inhibited the activation of the JAK/STAT pathway caused by the IL-6 and INF-γ treatment." (PMID 37446908, 2023). "Similar to carcinogenic hepatocytes, proliferation and stemness of intrahepatic cholangiocarcinoma (CCA) cells are enhanced by IL-6/gp130 signalling through the upregulation of EZH2 that mediates histone H3 methylation." (PMID 34047814, 2021). "Moreover, H19 is a biomarker for diagnosis of cholangiocarcinoma with high sensitivity and specificity and H19 can sponge Let-a/b, miR-372 and miR-373 to enhance IL-6 production, CXCR expression and tumor-related inflammation, and malignant behaviors of cholangiocarcinoma." (PMID 32272875, 2020). "Additionally, SGK-1 may promote the survival of cholangiocarcinoma cells by mediating the IL-6-related pathway." (PMID 33083492, 2020). "Thus, IL-6 may contribute to tumor growth by the modulation of miR-370 expression in cholangiocarcinoma cells." (PMID 28545228, 2017). "In cholangiocarcinoma tumor cells, the binding of STAT3 to the m6A writer gene results in the upregulation of m6A writers by cytokine IL-6, suggesting that m6A is a potential target in response to inflammation." (PMID 39136000, 2024). "For example, IL-6/STAT3-induced miR-17–92 targets JAK/STAT3 pathway inhibitor SOCS3 and PIAS3, generating a positive feedforward loop that amplifies IL-6/STAT3 signaling and contributes to cholangiocarcinoma cell proliferation and invasion." (PMID 35842651, 2022). "In cholangiocarcinoma cells, the JAK/STAT pathway activated by the proinflammatory cytokines IL-6 and IFN-γ in CCA cells was inhibited by quercetin treatment." (PMID 33995078, 2021). "Moreover, the finding that indicated increased IL-6 concentration in the cholangiocellular carcinoma group is consistent with the findings of the studies which reported that IL-6 may be used as a marker of cholangiocellular carcinoma and IL-6 can be used in anticancer chemotherapy." (PMID 29410961, 2017). "Downregulation of this miRNA cluster was recently shown to induce tumorigenesis due to a loss of inhibition of key inflammatory cytokines involved in the IL-6/signal transducer and activator 3 (STAT3) pathway in cholangiocarcinoma." (PMID 28208661, 2017). "Other tumor markers that have been studied for diagnosis of cholangiocarcinoma include transthyretin (TTR), interleukin-6 (IL-6), mucin-5AC (MUC5AC) and matrix metalloproteinase-7 (MMP-7)." (PMID 25355800, 2015). "Conversely, IL-6 induced hypomethylation of EGF receptor, leading to its enhanced expression and growth of cholangiocarcinoma cells." (PMID 24757565, 2014). "To test that, we stimulated two commonly used cholangiocarcinoma cell lines RPMI-7451 and Mz-ChA-1 with IL-6, an established hepcidin inducer." (PMID 21283681, 2011). "Interestingly two other calcium channel blockers, verapamil and diltiazem, also showed negative scores supporting the hypothesis that functional effects common to all drugs may be useful in reverting the systemic effects of IL-6 over-expression in cholangiocarcinoma." (PMID 21179572, 2010).
cholangiocarcinoma (continued). "Baricitinib treatment significantly reduced IL-6 and MCP-1 secretion in cholangiocarcinoma Conclusions: The patient-derived organoid model of PSC and liver tumors is a valuable tool for testing novel and established therapeutic strategies, including JAK inhibitors and chemotherapy regimens." (PMID 40426911, 2025). "Studies have found that the IL-6/AKT signaling pathway promotes Mcl-1 expression in cholangiocarcinoma, which in turn mediates tumor necrosis factor-related apoptosis-inducing ligand (TRAIL) resistance in cholangiocarcinoma patients." (PMID 37415745, 2023). "Amongst its mechanisms, genistein has shown a growth-inhibitory effect on human cholangiocarcinoma cells by reducing AKT and EGFR activation, as well as IL6 production, involving both oestrogen and oestrogen receptors, while also inhibiting inflammatory cell migration." (PMID 35884999, 2022). "For instance, the expression of HULC and H19 is triggered by oxidative stress to upregulate Interleukin-6 (IL-6) and the C-X-C chemokine receptor type 4 (CXCR4) sequestering Let-7a/b and miR-372/-373, respectively, to promote cholangiocarcinoma migration and invasion." (PMID 32492865, 2020). "Carbohydrate antigen 19-9 (CA19-9), leucine-rich α2-glycoprotein (LRG1), interleukin 6 (IL6), pyruvate kinase M2 (PKM2), cytokeratin 19 fragment (CYFRA21.1) and mucin 5AC (MUC5AC) have reported utility for differentiating cholangiocarcinoma (CCA) from benign biliary disease." (PMID 29707118, 2018). "Similarly, serum IL-6 concentration was significantly higher in the HCC and cholangiocellular carcinoma groups compared to the control group (p = 0.006 and p = 0.003, resp)." (PMID 29410961, 2017). "EGF, HGF/MET, VEGF, KRAS/MAPK, and IL-6/STAT pathways have been found to be deregulated in cholangiocarcinoma, but no effective therapies targeting these pathways have been developed." (PMID 26475437, 2015). "Interleukin 6 (IL-6)-mediated signal transducers and activators of transcription 3 (STAT-3) phosphorylation (activation) is aberrantly sustained in cholangiocarcinoma cells resulting in enhanced myeloid cell leukemia 1 (Mcl-1) expression and resistance to apoptosis." (PMID 25344679, 2014). "Braconi and colleagues verified that DNMT1 expression was elevated in some cholangiocarcinoma cell lines compared to nonmalignant human cholangiocyte lineage, and that increased was an indirect consequence of interleukin-6 (IL-6) over-expression." (PMID 21860617, 2012). "During carcinogenesis, senescence-related IL-6 activates gp130-STAT3 pathway using trans-signaling mode in hepatic progenitor cells or HCC progenitor cells to promote their proliferation, malignant transformation, and hepatocellular-cholangiocarcinoma carcinogenesis." (PMID 38890694, 2024). "Generally, IL-6 was secreted by noncancer stem cells in low-attachment culture conditions and enriched Oct4 gene expression by activating the IL-6R/JAK/STAT3 signaling pathway in chronic inflammatory disease, such as cholangiocarcinoma." (PMID 27809873, 2016).